ITGA11 (integrin subunit alpha 11)
Description:
Integrin alpha-11/beta-1 is a receptor for collagen.
Synonyms: HsT18964
Tractability: Antibody: its Gene Ontology location is reachable by antibodies, with high confidence; UniProt predicts a signal peptide or a membrane-spanning region.
Target class: Adhesion
Gene: Protein-coding gene on chromosome 15 (68,296,532 to 68,432,191, reverse strand). Ensembl gene ENSG00000137809.
Subcellular location: Membrane
Pathways (Reactome):
Extracellular matrix organization: Integrin cell surface interactions
Gene Ontology:
Molecular function: collagen binding; collagen binding involved in cell-matrix adhesion; collagen receptor activity; signaling receptor activity
Biological process: cell adhesion mediated by integrin; cell-matrix adhesion; collagen-activated signaling pathway; integrin-mediated signaling pathway; osteoblast differentiation; substrate-dependent cell migration; cell adhesion; cell-cell adhesion; muscle organ development
Cellular component: focal adhesion; integrin alpha11-beta1 complex; membrane; cell surface; integrin complex; plasma membrane
Genetic constraint (gnomAD): Loss-of-function variants: 84 observed, 118.79 expected, observed/expected ratio (o/e) 0.71, 90% interval 0.59 to 0.85. The upper end of that interval is the gene's LOEUF score, 0.85, which puts it in group 3 of 6, group 1 being the genes least tolerant of losing a copy. Missense variants: 1,358 observed, 1,494.6 expected, observed/expected ratio (o/e) 0.91, 90% interval 0.87 to 0.95. Synonymous variants: 644 observed, 603.15 expected, observed/expected ratio (o/e) 1.07, 90% interval 1 to 1.14.
Homologues: Orthologues: macaque ITGA11 (98% identical), chimpanzee ITGA11 (98% identical), pig ITGA11 (93% identical), dog ITGA11 (92% identical), mouse Itga11 (90% identical), rat Itga11 (90% identical), rabbit ITGA11 (89% identical), guinea pig ITGA11 (88% identical), tropical clawed frog itga11 (71% identical), zebrafish itga11a (59% identical), zebrafish itga11b (55% identical), Drosophila melanogaster scb (19% identical), and 4 more. Paralogues in human: ITGA10 (43% identical), ITGA1 (38% identical), ITGA2 (34% identical), ITGAD (28% identical), ITGAX (28% identical), ITGAM (27% identical), ITGAL (25% identical), ITGAE (23% identical), ITGA9 (21% identical), ITGA4 (20% identical), ITGA6 (20% identical), ITGA7 (20% identical), and 5 more.
Diseases named in the same sentence as ITGA11 in open-access papers:
ITGA11 is named in the same sentence as 67 diseases in open-access papers, as found by Europe PMC text mining. Sharing a sentence is not in itself a finding about the gene and the disease. The quoted sentences say what the papers report.
breast carcinoma (15 papers, 2017 to 2025). "It is reported that overexpressed ITGA11 is strongly linked to breast cancer suffers’ unfavorable prognosis." (PMID 34802381, 2021). "An overexpression of microenvironmental ITGA11 is associated with a high tumor grade and poor prognosis in breast cancer." (PMID 34503278, 2021). "The online data was consistent with the IHC data, suggesting high levels of either ITGA11 or Jab1/COPS5 was associated with worse survival in breast cancer." (PMID 29383106, 2017). "Survival analyses using the Kaplan–Meier method demonstrated that breast cancer patients with high levels of either ITGA11 or Jab1 had a significant association with worse prognosis." (PMID 29383106, 2017). "In the current study, we identified potential genes associated with breast cancer tumorigenesis by transcriptional network analysis and further validated ITGA11 from the STC analysis and a differentially expressed gene Jab1/COPS5 in clinical patients." (PMID 29383106, 2017). "Furthermore, RNA sequencing analysis of mRNA expression from the GEPIA online database revealed that ITGA11 was associated with Jab1/Cops5 in breast cancer patients." (PMID 29383106, 2017). "In addition, our immunohistochemistry data in breast cancer tissue indicated that Jab1 level was associated with ITGA11 levels in breast cancer and both ITGA11 and Jab1 levels were correlated with tumor grade." (PMID 29383106, 2017). "In breast cancer, ITGA11 has been found to play a role in the regulation of cancer-associated fibroblasts, tumor progression, and prognosis." (PMID 41373732, 2025). "Studies have shown that high expression of ITGA11 is associated with poor prognosis in various types of cancer, including gastric cancer, NSCLC, and breast cancer." (PMID 41373732, 2025). "The significance of the overexpression of EZH2 and ITGA11 in cancer progression and aggressiveness was also confirmed in breast cancer patients, using Kaplan-Meier survival analysis on The Cancer Genome Atlas (TCGA) dataset." (PMID 38664825, 2024). "High-level expression of ITGA11 or EZH2 was associated with poor survival and a decrease in recurrence-free survival of breast cancer patients." (PMID 38664825, 2024). "Worthy, the signature demonstrated to predict poor outcomes in breast cancer patients exhibiting high transcriptional levels of ITGA11, THBS1, FN1, EMP1, ITGA2, FYN, SPP1, and EMP2." (PMID 38937754, 2024). "In breast cancer, it was reported that ITGA11 promoted CAF invasive activity by interacting with PDGFRβ and promoting its downstream JNK activation, leading to the production of tenascin C, a pro-invasive matricellular protein." (PMID 34182990, 2021). "More importantly, ITGA11 has been widely reported to have significant values in glioblastoma, head and neck squamous cell carcinoma, and breast cancer." (PMID 34802381, 2021). "In agreement with the immunohistochemistry results, data from ONCOMINE indicated that ITGA11 and Jab1/Cops5 expression levels tend to be higher in breast cancer with higher grade." (PMID 29383106, 2017). "In agreement with the immunohistochemistry findings, the data from online database ONCOMINE indicated that ITGA11 and Jab1/Cops5 mRNA expression levels in breast cancer are much higher than those in normal breast tissue." (PMID 29383106, 2017). "ITGA11 and Jab1 were identified as biomarker for breast cancer." (PMID 38977697, 2024). "Our study identified ITGA11 and Jab1 as novel biomarkers for breast cancer." (PMID 29383106, 2017). "Taken together, we have identified ITGA11 and Jab1 as biomarkers in breast cancer." (PMID 29383106, 2017). "As expected, both ITGA11 and Jab1/Cops5 were overexpressed in breast cancer." (PMID 29383106, 2017). "We found high expression of ITGA11 was correlated with poor prognosis in breast cancer patients, which is in agreement with previous studies that Integrin expression levels are correlated with prognosis in glioblastoma, melanoma, gastric cancer, cervical cancer, and ovarian cancer." (PMID 29383106, 2017).
breast carcinoma (continued). "ITGA11 content in stroma contributes to the tumor growth and aggressiveness in both MDA-MB-231 xenograft models and breast cancer patients." (PMID 35159353, 2022). "PE‐Lap (FBP1, ITGA11, TRIM68, BCAT1, ZNF780A, UTP20 and GRB7) predicted outcomes of breast cancer patients treated with lapatinib." (PMID 34766125, 2020). "We also investigated the relationship between ITGA11 and Jab1/COPS5 and survival of breast cancer patients in GEPIA database." (PMID 29383106, 2017). "The axis of integrin α11-FAK-GLI-1/EZH2, formed in drug-resistant breast cancer cells, represents a shared positive feedback loop in both TAMR and ADR cells, which sustains the overexpression of EZH2 and ITGA11, thereby inducing drug resistance and CSC expansion." (PMID 38664825, 2024). "In order to validate the microarray results, we further carried out independent measurement of ITGA11 and Jab1 protein levels in breast cancer and noncancerous tissue samples using immunohistochemistry." (PMID 29383106, 2017). "Our previous analysis of open databases showed that ITGA11 expression was correlated positively with PDGFRB, ACTA2, TNC, COL1A1, and COL1A3 in human breast cancer, and the immunostainings showed that α11, PDGFRβ, and TNC were colocalized to CAF subsets in human breast cancer stroma." (PMID 36003785, 2022). "Furthermore, the present study, using a comparative large-scale transcriptome analysis of TAMR and ADR cells, identified ITGA11 as a master regulator that drives CSC expansion and drug resistance in breast cancer cells, independent of the type of anti-breast cancer drug." (PMID 38664825, 2024).
lung cancer (12 papers, 2018 to 2025). A malignant neoplasm involving the lung. "Three SNPs: rs1799732, rs5744256, and rs2306022 from DRD2, IL-18, and ITGA11 were among the five SNPs that MDR selected as best associated with lung cancer." (PMID 38137497, 2023). "The four genes, GREM1, LOXL2, ADAMTS12 and ITGA11, provide a candidate stromal signature that may be functionally implicated in lung cancer dissemination." (PMID 29503225, 2018). "To validate the function of differentially expressed genes in the LUAD morphogenesis, we performed shRNA knockdown (KD) of MPA-upregulated ITGA11 in a lung cancer cell line PC9." (PMID 38706836, 2024). "These recruitments of overexpressed ITGA11 CAFs into lung cancer stroma induce cancer cell migration through cancer cell–CAF interaction." (PMID 33682233, 2021). "ITGA11 has been reported to enhance the tumorigenicity of lung cancer by modulating IGF-2." (PMID 40275351, 2025). "Of these identified dysregulated prognosis-related ITGS, ITGA11 was identified as a potential oncogene in BRCA, GBM, LUAD, LUSC, STAD and THCA in this study, which has been confirmed in breast and lung cancer." (PMID 34222028, 2021). "The transcription levels of ITGA11, ITGB4 and ITGB8 between lung cancer and normal samples in ONCOMINE database." (PMID 31875161, 2019). "Using ONCOMINE database, we investigated the transcription levels of ITGA11, ITGB4 and ITGB8 in lung cancer vs. normal samples." (PMID 31875161, 2019). "Altogether our data suggest that expression of GREM1, LOXL2, ITGA11 and ADAMTS12 by MSCs enhances primary lung cancer metastasis." (PMID 29503225, 2018). "Furthermore, we analyzed ITGA11, ITGB4 and ITGB8 mRNA expression level in both lung cancer and normal tissues using the TCGA-LUAD and TCGA-LUSC original data." (PMID 31875161, 2019).
non-small cell lung carcinoma (10 papers, 2014 to 2024). A group of at least three distinct histological types of lung cancer, including non-small cell squamous cell carcinoma, adenocarcinoma, and large cell carcinoma. "The bioinformatics analysis revealed that ITGA11 is highly expressed in patients with non-small cell lung cancer and may become a diagnostic and prognostic biomarker." (PMID 33335550, 2020). "ITGA11 was found to enhance tumorigenicity of human non-small-cell lung cancer cells by regulating IGF2 expression in fibroblasts." (PMID 34257701, 2021). "It was reported that increased ITGA11 expression in cancer stroma was correlated with a poor clinical outcome in patients with non-small-cell lung cancer (NSCLC)." (PMID 34182990, 2021). "In this study, another gene, ITGA11, co-expressed with ENST00000499459, has attracted much attention because of its increased expression in cancer-associated fibroblasts (CAFs) leading to the progression of tumors, especially non-small cell lung cancer." (PMID 36463267, 2022). "In addition, ITGA11 has been reported to be correlated with lymph node metastasis, and serves as a potential marker for the diagnosis of non-small cell lung cancer." (PMID 25277193, 2014). "It has been reported that ITGA11 could serve as an important stromal factor in NSCLC, which can enhance tumorigenicity of human non-small cell lung cancer cells by regulating IGF2 expression in fibroblasts." (PMID 31875161, 2019).
gastric cancer (6 papers, 2017 to 2026). A primary or metastatic malignant neoplasm involving the stomach. "Oncomine analyses of cancer datasets have identified ITGA11 overexpression in breast, pancreas, lung, colorectal-, and gastric cancer, and we have recently shown that HNSCC tumors express α11 in their stroma." (PMID 31159419, 2019). "Zhang and colleagues investigated the integrin-subunit alpha 11 (ITGA11) expression level and its relation to PI3K/AKT signaling in gastric cancer." (PMID 39409942, 2024). "Gastric cancer (GC) is among the most frequent malignancies originating from the digestive system worldwide, while the role and specific mechanism of integrin-subunit alpha 11 (ITGA11) in GC remain unclear." (PMID 34802381, 2021).
bladder cancer (5 papers, 2024 to 2025). "PDGFRα+ ITGA11+ CAFs are associated with lymphovascular invasion (LVI) and early metastasis in early-stage bladder cancer, promoting lymphangiogenesis by recognizing the ITGA11 receptor SELE on lymphatic endothelial cells." (PMID 40766310, 2025). "Further, CHI3L1 from PDGFRα+ITGA11+ CAFs aligns the surrounding matrix to promote tumor cell intravasation, promoting lympho-vascular invasion and lymphatic metastasis of bladder cancer." (PMID 39726782, 2024). "PDGFRα+ITGA11+ CAFs are correlated with lympho-vascular invasion in bladder cancer, and these CAFs promote lympho-vascular invasion and lymphatic metastasis in bladder cancer." (PMID 39726782, 2024). "In urological cancers, a recent work incorporating ST and scRNA‐seq identified PDGFRα+/ITGA11+ fibroblasts that mediate lymphovascular invasion and lymphatic metastasis via ITGA11–SELE ligand‐receptor crosstalk in early stage bladder cancer." (PMID 39376738, 2024).
melanoma (5 papers, 2017 to 2024). A malignant, usually aggressive tumor composed of atypical, neoplastic melanocytes. "ITGA11 was elevated in the VLD-group when compared to non-VLD-CPI-treated melanoma patients." (PMID 36230498, 2022). "Notably, integrin alpha 11 (ITGA11), a transmembrane protein that mediates cell adhesion to the extracellular matrix, known for its proinflammatory role, was identified as the most upregulated protein in patients with ICI-induced VLLs (compared to melanoma patients treated with ICI without VLLs)." (PMID 38392077, 2024).
pancreatic cancer (5 papers, 2017 to 2024). "ITGA11 shown to be involved in regulating resistance to tumour therapy drugs in gastric and pancreatic cancers." (PMID 39539669, 2024). "The RT-qPCR data demonstrated increased RNA levels of integrin α11 (ITGA11) in the lung, pancreas, and skin tumor tissue relative to the normal tissues, with the greatest increase in α11 RNA to be found in the pancreas tumor." (PMID 31159419, 2019). "ITGA11 is also highly expressed in fibroblasts of head and neck cancer and pancreatic cancer." (PMID 33335550, 2020).
lung adenocarcinoma (4 papers, 2018 to 2021). A carcinoma that arises from the lung and is characterized by the presence of malignant glandular epithelial cells. "In our study, ONCOMINE analysis showed that mRNA expression level of ITGA11 was highly expressed in Lung Adenocarcinoma compared with that in normal controls." (PMID 31875161, 2019). "Moreover, supernatant media from lung adenocarcinoma cells (A549) strongly induced ITGA11 and COL11A1 expression, compared to that from normal epithelial cells (BEAS‐2B), without affecting expression of integrin α5 or β1 in HFL‐1." (PMID 33682233, 2021). "In a lung adenocarcinoma dataset from The Cancer Genome Atlas (TCGA), we observed a strongly significant correlation between ITGA11 and LOXL1 expression (Spearman r = 0.68, p-value < 0.0001), which we further validated in two other independent patient tumor datasets." (PMID 31121900, 2019).
idiopathic pulmonary fibrosis (3 papers, 2017 to 2025). Idiopathic pulmonary fibrosis (IPF) is a nonneoplastic pulmonary disease that is characterized by the formation of scar tissue within the lungs in the absence of any known cause. "Furthermore, ITGA11 has recently been shown to be overexpressed in lung samples from individuals with idiopathic pulmonary fibrosis." (PMID 28886342, 2017). "Fibroblasts derived from idiopathic pulmonary fibrosis (IPF) patients have higher collagen endocytic recycling capacity that is mediated by VPS33B and ITGA11." (PMID 39812558, 2025). "The mRNA expression of Itga11, Itgb8, Thbs1, and Thbs2 was significantly upregulated in the o-PF group, indicating the stronger activity of TGF-β in old rats when pulmonary fibrosis occurs." (PMID 36556326, 2022).
cardiomyopathy (2 papers, 2014 to 2021). A disease of the heart muscle or myocardium proper. "This gene encoding the ITGA11 subunit has also been shown to be up-regulated during myofibroblast differentiation in cardiomyopathy." (PMID 25051993, 2014). "However, a downregulation of genes in the cardiomyopathy pathways, primarily characterized by genes from the alpha integrin family (ITGA10, ITGA11, ITGAB), which bind collagen and are involved in the degradation of the extracellular matrix, was observed." (PMID 34943818, 2021).
colon cancer (2 papers, 2024 to 2025). "Furthermore, we achieved stable knockdown of ITGA11 in the human colon cancer cell line SW480 and subsequently evaluated the efficiency of this knockdown via Western blot analysis." (PMID 40766310, 2025). "For instance, ITGA11 is overexpressed in colon cancer samples when compared to normal adjacent tissue, while abnormal levels of ITGAV and ITGB6 in colorectal cancer has been associated with epithelial to mesenchymal transition, cancer progression, invasiveness, metastasis and a worse prognosis." (PMID 39167197, 2024).
colorectal cancer (2 papers, 2024 to 2025). A primary or metastatic malignant neoplasm that affects the colon or rectum. "Many of the other differentially expressed proteins have been described in colorectal cancer progression, including integrins of which ITGA11, ITGAV (also among the top 10 hub proteins) and ITGB6 were altered in this study." (PMID 39167197, 2024).
diabetic cardiomyopathy (2 papers, 2021). Diabetic cardiomyopathy is a disorder of the heart muscle in people with diabetes. "Studies have shown that ITGA11 contributes to regulating fibroblast differentiation in diabetic cardiomyopathy, mouse embryo implantation, atherosclerosis, and osteoarthritis." (PMID 34802381, 2021).
lung squamous cell carcinoma (2 papers, 2018 to 2019). "In contrast, the correlation in gene expression between ITGA11 and LOXL1 in lung squamous cell carcinoma and between ITGA11 and other LOX family members was not consistent in these three independent datasets." (PMID 31121900, 2019).